S100A8 (S100 calcium binding protein A8)
Diseases named in the same sentence as S100A8 in open-access papers (continued):
Sharing a sentence is not in itself a finding about the gene and the disease.
tumor (continued). "In contrast, other S100 proteins such as S100A6, S100A8, S100A9, and S100A11 are frequently upregulated in various malignancies, including BC, where they are linked to tumor-promoting functions." (PMID 41404073, 2025). "In pan-cancer analysis, S100P and S100A8 exhibited significantly altered expression in 8 and 12 tumor types, respectively." (PMID 40224483, 2025). "A strong positive correlation between TPS and IPS further supports the possibility of crosstalk between the tumor and immune compartments, consistent with prior evidence implicating S100A8 in the recruitment of MDSCs and modulation of inflammatory pathways." (PMID 41303754, 2025). "S100A8 contributes to the tumor microenvironment by binding to Toll-like receptor 4 (TLR4) and the Receptor for Advanced Glycation End-products (RAGE), activating NF-κB and inducing the production of pro-inflammatory cytokines." (PMID 40963634, 2025). "The S100A8/A9-positive cells identified in the stroma of PCP and the MPO-positive cells observed in both parenchyma and stroma were likely tumor-associated neutrophils." (PMID 40721446, 2025). "MDSCs are primarily generated in the bone marrow, and upon migrating to the tumor site, they can differentiate into immunosuppressive macrophages through the activation of the transcription factor NF-κB by S100A8/A9 proteins." (PMID 40299539, 2025). "In contrast to other malignancies where tumor-derived S100A8 promotes invasion and poor outcomes, its function in EC appears more immunomodulatory than oncogenic." (PMID 41303754, 2025). "The observed positive correlation between tumor and immune cell expression of S100A8 further supports the possibility of crosstalk between these compartments mediated by S100A8." (PMID 41303754, 2025). "Calprotectin, a heterodimer composed of the S100A8 and S100A9 proteins, has been increasingly recognized as a key player in tumor-associated inflammation." (PMID 40869349, 2025). "In particular, S100A8—which is expressed in both myeloid-lineage immune cells and tumor epithelial cells—has emerged as a critical mediator of tumor–immune interactions." (PMID 41303754, 2025). "BMDCs play a central role in cancer metastasis by orchestrating the immunosuppressive PMN through ECM remodeling, such as the production of MMP9 and S100A8/A9, which facilitate tumor cell extravasation and colonization." (PMID 40470380, 2025). "Future studies incorporating larger cohorts and molecular investigations are needed to validate the clinical utility of S100A8 as a prognostic or predictive biomarker and to further delineate its role in modulating the tumor–immune microenvironment." (PMID 41303754, 2025). "This study provides the first comprehensive assessment of S100A8 expression in both the tumor and immune compartments of endometrioid EC." (PMID 41303754, 2025). "Building upon these findings, our team has also explored the regulatory networks controlling S100A8/A9 expression in tumor cells." (PMID 40924339, 2025). "Multiple S100 proteins, including S100A2, S100A4, S100A8, and S100A9, are significantly upregulated in EC compared with those in the normal endometrium, and their expression has been linked to tumor proliferation, invasion, and progression." (PMID 41303754, 2025). "This divergence likely stems from the unique hormonal and inflammatory microenvironment of the endometrium, where immune cell-derived S100A8 plays a dominant role in shaping tumor–immune crosstalk." (PMID 41303754, 2025). "Our results showed that the expression of the S100A9, as well as S100A8, mRNAs were induced in Fusobacterium-high tumor samples." (PMID 40895532, 2025). "Neutralizing antibodies against S100A8/A9 have demonstrated tumor-suppressive and immune-modulatory effects in animal studies, particularly through attenuation of myeloid-derived suppressor cell recruitment." (PMID 41404073, 2025).
tumor (continued). "For instance, increased expression of S100A8 and S100A9 is associated with pro-inflammatory signaling and enhanced tumor cell migration." (PMID 41404073, 2025). "S100a8, S100a9, and the S100a8/a9 heterodimer are involved in cancer development, progression, and metastasis by interfering with tumor metabolism and microenvironment." (PMID 39796176, 2025). "IHC analysis of S100A8 expression demonstrated heterogeneous patterns across tumor and immune compartments." (PMID 41303754, 2025). "S100A8 and S100A9, for instance, activate the MAPK and NF-κB pathways, which in turn promote cytokine production, leukocyte recruitment, and tumor-associated inflammation." (PMID 41404073, 2025). "S100 family members such as S100A8, S100A9, S100A13, and S100A6 are upregulated in advanced BC and are associated with tumor progression, immune suppression, and poor prognosis." (PMID 41404073, 2025). "The results not only confirmed increased expression of S100A8/A9 in mesenchymal cells but also showed a significant elevation in tumor glandular epithelial cell plasma compared to normal tissues." (PMID 38817853, 2024). "To validate our findings, we established both subcutaneous and tail vein tumor models in nude mice using CT26 cells that overexpressed S100A8." (PMID 38817853, 2024). "Mechanistically, Sec C can inhibit the proliferation, migration, and self-renewal ability of tumor cells by downregulating Ca2+-binding protein S100A8." (PMID 38607060, 2024). "Together with HT29 cells, we believed that S100A8 promoted the movement of tumor cells and played an obstructive role in the inhibitory effect of Sec C on tumor cell migration." (PMID 38607060, 2024). "S100a8 hallmarks inflammatory TAMs, and Htra3 function as a tumor suppressor by stimulating apoptosis in LC." (PMID 38245882, 2024). "Our results highlighted S100A9 and S100A8 as more-abundant proteins in the superficial tumor samples, in accordance with previous studies." (PMID 39195201, 2024). "We have reason to believe that targeting S100A8 should improve tumor resistance, especially in the context of CAM-DR, and a new study should be investigated in the future." (PMID 38361783, 2024). "Meanwhile, the HT29 cell groups also showed larger spheres, even with the pressure of Sec C. This fully proved that S100A8 enhanced the self-renewal ability of tumor cells to oppose Sec C." (PMID 38607060, 2024). "Combining all results for S100A8, we concluded that S100A8 positively participated in the proliferation, migration, sphere formation, and drug resistance of tumor cells." (PMID 38607060, 2024). "In vitro experiments suggested that inhibition of S100A8 should promote cell apoptosis and suppress tumor growth." (PMID 38361783, 2024). "To assess the influence of S100A8 on tumor cell behavior, we conducted MTT and Transwell invasion assays, both performed 24 hours post-transfection of CT26 cells with an S100A8 overexpression plasmid." (PMID 38817853, 2024). "Our previous study found that the density of S100A8+ cells in the tumor invasivefront (TIF) was an indicator of a good prognosis in CRC." (PMID 38711020, 2024). "In order to explore these opportunities further, the role of tissue-resident S100A8/A9 in NET-rich tumor beds needs to be characterized more in detail." (PMID 39700646, 2024). "A distinct tumor cell subpopulation characterized by elevated S100A8 expression exhibited high copy number variation, high stemness, and low differentiation." (PMID 39691708, 2024). "S100A8 has been associated with regulation of the TME, potentially influencing the adhesive properties of tumor cells." (PMID 38361783, 2024). "We also carried out an EdU assay to test the DNA replication level of tumor cells, and we found that S100A8 enhanced DNA synthesis to counter Sec C treatment." (PMID 38607060, 2024).
tumor (continued). "Recent studies have also shown that upregulated S100A8 and S100A9 and their associated inflammatory factors were presented in the tumor microenvironment since the inflammation conditions are strongly involved in the neoplastic process and cancer development." (PMID 39575241, 2024). "It has also been shown that S100A8/A9, S100A9, and S100A8 have the potential to be tumor diagnostic or prognostic biomarkers." (PMID 39594999, 2024). "Patients with positive membranous or nuclear GSDMB expression had more abundant S100A8+ immune cells in the tumor invasive front." (PMID 38711020, 2024). "Subsequent works have shown that blocking the effect of S100A9, S100A8 or S100A8/A9 in various ways in a tumor setting, can reduce immune suppression and tumor growth and affect the accumulation of myeloid cell populations." (PMID 39497822, 2024). "S100A8, a calcium-binding protein belonging to the S100 family, is involved in immune responses and multiple tumor pathogens." (PMID 38361783, 2024). "Along with HT29 cells, it was obvious that Sec C displayed a stronger effect on the movement of tumor cells after S100A8 was downregulated." (PMID 38607060, 2024). "The pro-inflammatory mediator S100A8/A9 is involved in promoting inflammatory responses to infections and autoimmune diseases, and has been identified as a potent amplifier of tumor invasion and metastasis." (PMID 38404689, 2024). "When the body is in a pathological state, such as inflammation and tumor, the S100A8 and S100A9 levels are abnormally elevated." (PMID 39575241, 2024). "S100A8 and its cognate-binding partner S100A9 exhibit potential prognostic biomarkers for reactivation of dormant tumor cells, prediction of metastatic risk and therapeutic responses failure in several malignancies, including BC." (PMID 39830522, 2024). "On the contrary, after treatment of S100A8/S100A9 in some tumor cells, it can induce cell death through apoptosis and autophagy, and this process would be rectified using N-acetyl-L-cysteine (NAC) through decreasing mitochondria reactive oxygen species (ROS)." (PMID 38361783, 2024). "Next, we investigated the potential of a combination therapy targeting both PIM and PD-1 or PD-L1 to either inhibit continued tumor growth, or to induce tumor regression in a manner proportional to tumoral S100A8/A9 levels." (PMID 38378783, 2024). "Currently, S100A8 plays complex and multifaceted roles, with both tumor inhibition and promotion functions depending on the different tumor types." (PMID 38361783, 2024). "In tumor cells, S100A8 and S100A9 induce phenotypic changes by influencing calcium ion concentrations and other pathways." (PMID 38817853, 2024). "Recent discoveries implicate BRCA1, a known tumor suppressor, as essential for regulating the levels of S100A8 and S100A9 in the body." (PMID 39057065, 2024). "Targeting CD11b reduces myeloid cell infiltration, particularly in cells expressing S100A8 and matrix metalloproteinase-9, which are key factors in tumor regrowth." (PMID 39452540, 2024). "Meanwhile, Sec C suppressed the stemness traits by decreasing S100A8 expression to inhibit tumor cell progression." (PMID 38607060, 2024). "Further, experimental anti-S100A8 and -A9 neutralizing antibodies reduced tumor growth and metastasis of a lung cancer model." (PMID 38378783, 2024). "To clarify the relationship between C1 S100A8+ TCs subpopulation and tumor, we performed various enrichment analyses on cell subpopulations." (PMID 39691708, 2024). "(iv) Consequently, P-BS-CM1 → P-CM2 substantially regressed pulmonary PMN hallmarks like LOX accumulation, BMDC recruitment, S100A8 secretion, and E-cadherin expression to levels close to healthy tumor-free mice, whereas free BS and P-BS had limited effects." (PMID 38553476, 2024). "Throughout all stages, from inflammation to tumor development, we noted a significant increase in the expression of S100A8/A9." (PMID 38817853, 2024).
tumor (continued). "The pro-tumor effect of Paquinimod was somewhat unexpected, as previous studies targeting S100A8 and/or A9 signaling has demonstrated anti-tumor effects." (PMID 39497822, 2024). "Previous studies have confirmed the pivotal role of the extracellular secretory proteins S100A8/S100A9 in promoting the proliferation of tumor cells and facilitating invasive metastasis." (PMID 38817853, 2024). "Generally, the role of S100A8 in multiple tumors is highlighted as a promotor of tumor invasion, TME formation, and drug resistance, however, there has been no direct report on relationship between S100A8 and DLBCL." (PMID 38361783, 2024). "Due to the apparent link between S100A8/A9 and neutrophils, we dealt with the influence of systemic neutrophilia on tumor progression via Kaplan-Meier estimation." (PMID 39700646, 2024). "Among them, we discovered that TCs exhibiting elevated levels of S100A8 were exclusively derived from tumor tissue specimens." (PMID 39691708, 2024). "Similar to CCN1, S100A8 was firstly reported to take part in reconstruct tumor microenvironment by recruitment of immune cells, leading to tumor growth, metastasis, and premetastatic niche formation." (PMID 39659236, 2024). "There is a possibility that in tumor-free mice, S100A8/S100A9 exist mainly in the form of tetramers and that TQ is unable to bind S100A9 and block its effects." (PMID 36923707, 2023). "We previously reported that Eritoran, a TLR4 inhibitor, inhibited S100A8-mediated cell migration and tumor progression in tumor-bearing mice." (PMID 36932197, 2023). "In several mouse tumor models, the inhibition of S100A8/A9, the regulatory factors of MDSCs, has been shown to restrict tumor growth by diminishing the accumulation of MDSCs." (PMID 38045829, 2023). "These extracellular microparticles are able to fuse with cancer and normal lung cells and inhibit tumor cell migration, as well as reduce inflammation in the tumor microenvironment by decreasing the release of S100A8/A9 and IL-6." (PMID 36670988, 2023). "The MDSCs also expressed RAGE, HMGB1, and S100A8 and A9 transcripts and Western blots confirmed the presence of the corresponding proteins, although only tumor-induced MDSCs contained S100A8/A9 heterodimers." (PMID 36831371, 2023). "In those patients, the correlation between the serum and tumor tissue levels was marginal for S100A8 (r = 0.38, P = 0.060), while a significant positive correlation was noted between the serum and tumor tissue levels of S100A9 (r = 0.41, P = 0.042)." (PMID 37280516, 2023). "In a study of various cancer cell lines, it was observed that reduced S100A8/9 levels induced tumour cellular growth and enhances proliferation." (PMID 36855072, 2023). "Using specific antibodies, changes of S100A8/A9 in tumor-bearing mice can be monitored to evaluate the establishment of an immunosuppressive state and a metastasis-permissive microenvironment." (PMID 37701037, 2023). "Two weeks after tumor inoculation, BM from DP42-bearing mice had a significantly higher amount of S100A8/S100A9 than tumor-free mice." (PMID 36923707, 2023). "Initially, we proposed that S100A8 induced in the lungs by the primary tumor contributed to pulmonary premetastatic niche formation." (PMID 36932197, 2023). "Since S100A8/A9 is a prominent mediator of cancers, targeting S100A8/A9 to explore novel strategies in tumor treatment is promising." (PMID 37701037, 2023). "The results also indicated that higher levels of S100A8 were correlated with enlarged tumor size (* p = 0.030), advanced clinical stage (** p = 0.007), and positive surgical margins (* p = 0.015)." (PMID 37174723, 2023). "Like 67NR and 4T07 tumors, EO771 tumor induced expansion of Gr1+CD11b+Ly6G+ neutrophils and overproduction of S100A8/A9 in the scaffolds and lungs of C57 mice." (PMID 37553342, 2023). "Positive S100A8 staining was observed both in epithelial tumor cells and in polymorphonuclear (PMN) cells." (PMID 37450087, 2023).
tumor (continued). "Some studies have shown that low S100A8/A9 concentrations can not only stimulate the proliferation and migration of vascular endothelial cells in vitro, but also promote tumor cell vascularization to benefit their growth." (PMID 37701037, 2023). "In tumor-bearing mice, S100A8 was expressed in infiltrating monocytes at the tumor surrounding area as well as found in intratumoral areas." (PMID 36932197, 2023). "Collectively, these studies demonstrate that the RAGE ligands, S100A8 and A9, produced by MDSCs and/or by tumor cells in the TME, are key molecules for driving the accumulation and function of MDSCs in individuals with cancer." (PMID 36831371, 2023). "The data demonstrated the presence of S100A8 in tumor cells, especially in the cytoplasm, along with nuclear staining." (PMID 37174723, 2023). "In this study, we focused on S100A8 as a therapeutic target against aggressive cancers in an effort to improve tumor-immune responses." (PMID 36932197, 2023). "Since proliferation is one of the most important tumor characteristics, many studies have focused on the function of S100A8/A9 in it." (PMID 37701037, 2023). "The abundance of cell−cell interactions in mast cells/CD4 T cells/S100A8+ macrophages/tumor cells compared to other cells was higher in responders than in nonresponders." (PMID 37152010, 2023). "As described, RAGE ligands S100A8/A9 and HMGB1 are strongly implicated in many aspects of neoplasia." (PMID 36831371, 2023). "In the tumor array, correlations were observed between S100A8 and S100A4 (R = 0.66), S100A9 (R = 0.62) and S100A10 (R = 0.46)." (PMID 37627239, 2023). "We found increased S100A8 CN (≥ 4) in tumor epithelial cells in 20% of the tumors, increased S100A8 protein expression in 15%, and ≥ 10 infiltrating S100A8 + polymorphonuclear cells in 19%." (PMID 37450087, 2023). "The time ratio for this variable was estimated to be 0.2 (95% CI 0.10–0.42), meaning that the average estimated lifespan of patients in this group, from time of diagnosis, was 20% of that of cases with less than 1% of S100A8 + tumor epithelial cells." (PMID 37450087, 2023). "S100A8 protein expression in tumor epithelial cells identifies a subgroup of predominantly non-luminal tumors with a high mean age at diagnosis and significantly worse prognosis." (PMID 37450087, 2023). "As most tumor cells including SW480 cells also express TLR4, S100A8 inhibitory peptides would target both the tumor microenvironment and tumor cells." (PMID 36932197, 2023). "The xenograft models indicated that DACH1 expression significantly retarded tumor growth and downregulated S100A8/A9 protein abundance." (PMID 38093319, 2023). "The IHC staining using one TMA was conducted to interrogate S100A8 expression in normal and tumor tissues." (PMID 38093319, 2023). "If S100A8/A9 cooperates with other immune factors to activate suppressive pathways in tumor cells, it would lead to cell death." (PMID 37701037, 2023). "Studies have shown that S100A8 expression is positively correlated with PD-L1 levels in tumor samples and can induce PD-L1 in macrophages by activating PI3K/Akt, MAPKs, NF-κB, and STAT3 to increase PD-L1 transcription." (PMID 37701037, 2023). "Among them, COPS3, DYHC1, and S100A8 are unfavorable for tumor recurrence and survival, in contrast to A2M and Serpine1, low levels of which show an association with better DFS." (PMID 37174723, 2023). "Simultaneously, the S100A8/A9–SSSRs axis participates in many aspects of tumor initiation and development, usually involving MAPKs, NF-κB, PI3K/Akt, and mTOR along with the assistance of VEGF, YAP, Nrf2, and HIF-1." (PMID 37701037, 2023). "In this study, we revealed that SERPINB3 modulated the TME toward an immunosuppressive phenotype by upregulating CXCL1/8 and S100A8/A9 production to facilitate tumor growth and impede the success of RT." (PMID 37279067, 2023).